TARDBP (TAR DNA binding protein)
Diseases named in the same sentence as TARDBP in open-access papers (continued):
Sharing a sentence is not in itself a finding about the gene and the disease.
amyotrophic lateral sclerosis (continued). "Amyotrophic lateral sclerosis (ALS) and frontotemporal dementia (FTD) share a common mechanism for mitochondrial toxicity and neurodegeneration caused by protein misfolding and aggregation of mutant superoxide dismutase 1 (SOD1), TAR DNA-binding protein 43 (TDP-43), and RNA-binding protein FUS." (PMID 33922020, 2021). "Amyotrophic lateral sclerosis (ALS), also known as motor neuron disease (MND), is a neurodegenerative condition that is pathologically characterized by the accumulation of ubiquitinated intracellular inclusions containing TAR DNA-binding protein 43 (TDP-43)." (PMID 33815058, 2021). "In 2006, the predominately nuclear TAR DNA-binding protein 43 (TDP-43) was identified as a key component of the insoluble and ubiquitinated inclusions in the brains of patients suffering from amyotrophic lateral sclerosis (ALS) and frontotemporal lobar degeneration (FTLD or FTLD-TDP) diseases." (PMID 32308803, 2020). "The trans-activating response region DNA-binding protein 43 (TARDBP, TDP-43) is a product of a causative gene for amyotrophic lateral sclerosis (ALS), and its disease-associated mutations cause its accumulation in the cytoplasm of cells in ALS-related lesions in the brain." (PMID 30759234, 2019). "TAR DNA-binding protein (TDP-43) is a ubiquitously expressed nuclear protein, which participates in a number of cellular processes and has been identified as the major pathological factor in amyotrophic lateral sclerosis (ALS) and frontotemporal lobar degeneration (FTLD)." (PMID 30922385, 2019). "In the case of amyotrophic lateral sclerosis (ALS) and frontotemporal dementia (FTD), aggregates of two RNA-binding proteins (RBPs), the TAR DNA-binding protein of 43 kDa (TDP-43) and the fused in sarcoma (FUS) gene product, are found in the cytoplasm of affected neurons." (PMID 30486313, 2018). "Abnormal accumulation of TAR DNA-binding protein 43 (TDP-43) in the cytoplasm and its disappearance from the nucleus are pathological features of amyotrophic lateral sclerosis and frontotemporal dementia (ALS/FTD) and are directly involved in the pathogenesis of these conditions." (PMID 29449800, 2018). "TAR DNA binding protein of 43 kilodaltons (TDP-43) is the major pathological substrate in frontotemporal lobar degeneration with TDP-43 pathology (FTLD-TDP) and most cases of amyotrophic lateral sclerosis (ALS)." (PMID 24466128, 2014). "Amyotrophic lateral sclerosis (ALS) and frontotemporal dementia (FTD) are progressive neurodegenerative diseases characterised by TAR DNA-binding protein 43 kDa (TDP-43) pathology." (PMID 41546756, 2026). "In amyotrophic lateral sclerosis (ALS) and frontotemporal dementia (FTD), the abnormal accumulation of TAR DNA-binding protein 43 (TDP-43) disrupts mitochondrial function, leading to excessive generation of ROS." (PMID 40298834, 2025). "Amyotrophic lateral sclerosis (ALS) and frontotemporal dementia (FTD) are progressive and ultimately fatal diseases characterised by 43-kDa TAR DNA-binding protein (TDP-43) pathology." (PMID 40502782, 2025). "Phosphorylated Tar-DNA binding protein 43 (TDP-43), for example, forms pathological axonal aggregates in amyotrophic lateral sclerosis (ALS), including G3BP1." (PMID 40806415, 2025). "In postmortem brain tissues of patients with sporadic amyotrophic lateral sclerosis (ALS), the dimerization ability of TAR DNA‐binding protein 43 (TDP‐43) is impaired, accompanied by an accumulation of insoluble TDP‐43." (PMID 40847753, 2025). "None of the MFN2-amyotrophic lateral sclerosis patients tested positive for the pathogenic C9orf72 gene expansion, nor did they exhibit mutations in the SOD1 gene or the known mutational hotspots of the TARDBP (exon 6) and FUS (exons 13-14-15) genes." (PMID 39315308, 2024). "Here, we study TDP-43 (TAR DNA-binding protein 43), which often aggregates in the neurons of patients with ALS (amyotrophic lateral sclerosis) and other diseases." (PMID 38892445, 2024).
amyotrophic lateral sclerosis (continued). "Accumulation of cytoplasmic inclusions of TAR-DNA binding protein 43 (TDP-43) is seen in both neurons and glia in a range of neurodegenerative disorders, including amyotrophic lateral sclerosis (ALS), frontotemporal dementia (FTD) and Alzheimer’s disease (AD)." (PMID 37747929, 2023). "Transactivation response DNA binding protein 43 kDa (TDP-43/TARDBP) is a pathological protein observed in amyotrophic lateral sclerosis (ALS) and frontotemporal lobar degeneration (FTLD), and a subset of aged people also show TDP-43-related pathology." (PMID 36555399, 2022). "We previously reported the diagnostic and prognostic performance of neurofilament light chain (NfL), TAR DNA-binding protein 43 (TDP-43), and total tau (t-tau) in cerebrospinal fluid (CSF) and plasma as amyotrophic lateral sclerosis (ALS) biomarkers." (PMID 34843548, 2021). "Similarly, while cytoplasmic TDP-43 inclusions are a hallmark of amyotrophic lateral sclerosis (ALS), and rare pathogenic variants in the TARDBP gene have been linked to ALS, to date, no large GWAS or meta-analysis of ALS GWAS has detected a signal near the TARDBP gene." (PMID 31261387, 2019). "They include amyloid β (Aβ), a hallmark of Alzheimer disease, α-synuclein, a feature of Parkinson’s and Lewy body disease, and TAR DNA-binding protein 43 (TDP-43), typical of frontotemporal lobar degeneration (FTLD) and amyotrophic lateral sclerosis (ALS)." (PMID 30563563, 2018). "TAR DNA-binding protein 43 (TDP-43) is a key player in neurodegenerative diseases including frontotemporal lobar degeneration (FTLD) and amyotrophic lateral sclerosis (ALS)." (PMID 29802307, 2018). "In Amyotrophic Lateral Sclerosis (ALS), the abundant protein superoxide dismutase (SOD1) or the TAR-DNA binding protein TDP-43 can aggregate in motor neurons." (PMID 30401824, 2018). "Aggregation of TAR-DNA-binding protein 43 (TDP-43) and of its fragments TDP-25 and TDP-35 occurs in amyotrophic lateral sclerosis (ALS)." (PMID 27466192, 2016). "Only in recent years was Tar-DNA binding protein 43 (TDP-43), a widely expressed nuclear protein, recognized as the major protein in cases of FTLD with ubiquitin-immunoreactive inclusions with or without motor neuron disease and in sporadic motor neuron disease or amyotrophic lateral sclerosis." (PMID 25419243, 2014). "The major aggregating proteins in amyotrophic lateral sclerosis (ALS) are superoxide dismutase 1 (SOD1), TDP-43 (TARDBP) and FUS." (PMID 25358814, 2014). "Mutations of RNA binding proteins, including TAR DNA-binding protein-43 (TDP-43) and fused in sarcoma/translocated in liposarcoma (FUS/TLS), have been described in amyotrophic lateral sclerosis (ALS)." (PMID 23835137, 2013). "Several studies have shown that ubiquitinated Tar-DNA Binding Protein 43 (TDP-43) is a component of inclusion bodies in both FTLD-U and Amyotrophic Lateral Sclerosis (ALS) although other ubiquitinated proteins are also present in these inclusion bodies in ALS." (PMID 19860916, 2009). "Amyotrophic lateral sclerosis (ALS) is a fatal neurodegenerative disease characterised by motor neuron degeneration, muscle weakness, paralysis, and eventual death, with TAR DNA-binding protein 43 (TDP-43) pathology observed in almost all cases." (PMID 40824324, 2025). "Liraglutide treatment did not, however, improve motor function in SOD1G93A and TAR DNA-binding protein (TDP-43)Q331K transgenic Amyotrophic lateral sclerosis (ALS) mice models, according to earlier investigations." (PMID 40964464, 2025). "Co-occurrence with other misfolded protein pathologies, such as phosphorylated α-synuclein (pSyn) typical of Parkinson’s disease (PD), or TAR DNA-binding protein 43 (TDP-43), found in pathological deposit in amyotrophic lateral sclerosis (ALS) or frontotemporal dementia (FTD) is frequently observed." (PMID 39954093, 2025).
amyotrophic lateral sclerosis (continued). "The TDP-43 protein (TAR DNA-binding protein 43Kd) is a key player in the pathophysiology of neurodegenerative diseases known as TDP-43 proteinopathies, including amyotrophic lateral sclerosis (ALS) and frontotemporal lobar dementia (FTLD)." (PMID 39336748, 2024). "The TDP-43 protein (TAR DNA binding protein 43) accumulates in the cytoplasm of neurons in patients with amyotrophic lateral sclerosis (ALS) and frontotemporal dementia (FTLD), which led to the classification of many ALS and FTLD cases as proteinopathies." (PMID 37508002, 2023). "In most cases of amyotrophic lateral sclerosis, there is no family history associated, but in about 10% of cases, a dominantly inherited autosomal mutation occurs in distinct genes, such as in superoxide dismutase 1 (SOD1), C9orf72, and TAR DNA-binding protein 43 (TDP-43) genes." (PMID 37259454, 2023). "In disease, TARDBP is known to be frequently mutated in sporadic and familial amyotrophic lateral sclerosis (ALS), as well as in patients with frontotemporal lobar degeneration (FTLD), providing evidence of a direct link between TARDBP abnormalities and neurodegeneration." (PMID 31186504, 2019). "The transactive response DNA-binding protein 43 (TARDBP; TDP-43) has been identified to play a crucial role in the development of neurodegenerative diseases, especially in amyotrophic lateral sclerosis (ALS) and frontotemporal lobar degeneration with ubiquitin-positive inclusions (FTLD-U)." (PMID 29787578, 2018). "Amyotrophic lateral sclerosis (ALS) and frontotemporal dementia (FTD) are neurodegenerative diseases that are characterised by the deposition of pathological protein aggregates composed of TAR DNA-binding protein 43 (TDP-43 or TARDBP)." (PMID 24424030, 2014). "Tar DNA binding protein 43 (TDP-43) is the major component of pathological deposits in frontotemporal lobar degeneration with TDP-43 inclusions (FTLD-TDP) and in amyotrophic lateral sclerosis (ALS)." (PMID 23922830, 2013). "Amyotrophic lateral sclerosis (ALS) and frontotemporal lobar degeneration (FTLD) are neurodegenerative disorders that are characterized by cytoplasmic aggregates and nuclear clearance of TAR DNA-binding protein 43 (TDP-43)." (PMID 23727833, 2013). "Missense mutations in the TIA1 gene, responsible for Welander distal myopathy (WDM) and amyotrophic lateral sclerosis (ALS), are characterized by delayed SG disassembly and accumulation of non-dynamic SGs that harbor cytotoxic TAR DNA-binding protein 43 (TARDBP, TDP43)." (PMID 35205152, 2022). "TAR DNA-binding protein of 43 kDa (TDP-43) is a major component of intracellular aggregates formed in brains of the patients with frontotemporal lobar degeneration (FTLD) and amyotrophic lateral sclerosis (ALS), which are correctively referred to as TDP-43 proteinopathies." (PMID 33115537, 2020). "Most cases of amyotrophic lateral sclerosis (ALS) and frontotemporal dementia (FTD) have cytoplasmic inclusions of TAR DNA-binding protein 43 (TDP-43) in neurons and non-neuronal cells, including astrocytes, which metabolically support neurons with nutrients." (PMID 32265469, 2020). "The RNA-binding proteins TDP-43 (TAR DNA-binding protein of 43 kDa) and FUS (Fused in sarcoma) have become infamous over the past years as being the main culprits in two fatal neurodegenerative diseases, ALS (amyotrophic lateral sclerosis) and FTD (frontotemporal dementia)." (PMID 29728564, 2018). "Recently, the 43 kDa nuclear protein TAR DNA-binding protein (TDP-43) has been identified as a major component of UBIs aggregated proteins in sporadic and familial frontotemporal lobar degeneration with ubiquitinated inclusions (FTLD-U) as well as sporadic amyotrophic lateral sclerosis (ALS)." (PMID 27769241, 2016).
frontotemporal dementia (1,184 papers, 2008 to 2026). Frontotemporal dementia (FTD) comprises a group of neurodegenerative disorders, characterized by progressive changes in behavior, executive dysfunction and language impairment, as a result of degeneration of the medial prefrontal and frontoinsular cortices. "In 2010, an international collaboration identified three SNPs in TMEM106B as the main susceptibility loci for frontotemporal lobar degeneration with TAR DNA binding protein (TDP-43) inclusions (FTLD-TDP)." (PMID 38674351, 2024). "Progranulin (PGRN) haploinsufficiency due to progranulin gene (GRN) variants can cause frontotemporal dementia (FTD) with aberrant TAR DNA-binding protein 43 (TDP-43) accumulation." (PMID 38347588, 2024). "Patients with FTD due to GRN mutations (FTD-GRN) develop frontotemporal lobar degeneration with TAR DNA-binding protein 43 (TDP-43) pathology type A, which is characterized by TDP-43 aggregation and neuronal loss, particularly in layer II/III of the cortex." (PMID 38840181, 2024). "For instance, mutations in the TAR-DNA-binding-protein 43 (TDP-43) also result in familial forms of ALS as well as frontotemporal dementia." (PMID 36358945, 2022). "Homozygous GRN mutations lead to neuronal ceroid lipofuscinosis, and heterozygous mutations in GRN in humans lead to frontotemporal dementia (FTD-GRN) with TAR DNA-binding protein-positive inclusions (FTD-TDP)." (PMID 36618392, 2022). "Along with aggregation of TAR DNA-binding protein 43 (TDP-43), Tau pathology is also a hallmark of frontotemporal dementia (FTD)." (PMID 36397124, 2022). "The redistribution of the nucleus protein TAR DNA-binding protein 43 (TDP-43) in the cytosol of neurons was previously associated with frontotemporal dementia and TDP-43 mutant ALS." (PMID 36362259, 2022). "Most notably, the understanding of frontotemporal dementia has been further advanced by the identification of disease causing mutations in the genes for TAR DNA-binding protein-43 (TARDBP), progranulin (GRN) and C9orf72-SMCR8 complex subunit (C9ORF72)." (PMID 35120450, 2022). "Heterozygous loss-of-function mutations of the neurodegenerative disease protein PGRN (progranulin) result in TDP-43 (TAR DNA binding protein-43) inclusions and cause frontotemporal lobar degeneration." (PMID 33800981, 2021). "In 69–83% of cases, the underlying pathology is frontotemporal lobar degeneration (FTLD) transactive response DNA-binding protein TAR DNA-binding protein-43 (TDP-43) type C pathology." (PMID 31848674, 2020). "Haploinsufficiency of the gene encoding progranulin (PGRN) leads to frontotemporal lobar degeneration (FTLD) with TAR DNA binding protein 43 (TDP‐43) deposition (FTLD‐TDP)." (PMID 30482868, 2018). "Loss-of-function mutations in progranulin (GRN) and a non-coding (GGGGCC)n hexanucleotide repeat expansions in C9ORF72 are the two most common genetic causes of frontotemporal lobar degeneration with aggregates of TAR DNA binding protein 43 (FTLD-TDP)." (PMID 29855382, 2018). "The pathogenesis of frontotemporal lobar degeneration (FTLD) is associated with the aberrant phosphorylation of a RNA/DNA binding protein TDP-43 (TAR DNA binding protein 43)." (PMID 29780404, 2018). "In a meta-analysis of PPA LV series from different centers, the remaining 38 % were due to Tar DNA binding protein 43 (TDP)-associated frontotemporal lobar degeneration (FTLD), with 5–10 % caused by tau-associated FTLD." (PMID 27097664, 2016). "Recently it was established that mutant TAR DNA binding protein-43 (TDP-43) is associated with the development of frontotemporal lobar degeneration and ALS." (PMID 24575040, 2014). "Therefore, we next focused on the canonical CMA client TARDBP/TDP-43, whose aberrant function is associated with frontotemporal dementia." (PMID 37876225, 2024).
frontotemporal dementia (continued). "Sixty-three patients carrying the p.M337V variant in TARDBP from this study and previous reports delineated young age of onset (51.6 years), high frequency of bulbar onset patients (61.9%), and low comorbidity of frontotemporal dementia." (PMID 37914747, 2023). "There exists a genetic, clinical, and pathological overlap between ALS and frontotemporal dementia (FTD), whereby several genes (e.g., C9orf72, TARDBP, TBK1) have been associated with both conditions." (PMID 38986433, 2025). "Progranulin-deficient frontotemporal dementia (GRN-FTD) is a major cause of familial FTD with TAR DNA-binding protein 43 (TDP-43) pathology, which is linked to exon dysregulation." (PMID 40913764, 2025). "GRN mutations were first identified in 2006 as a cause of frontotemporal dementia (FTD) with TAR DNA-binding protein 43 (TDP-43) inclusions." (PMID 40234992, 2025). "Heterozygous mutations in the GRN gene lead to reduced levels of progranulin (PGRN), causing frontotemporal dementia (FTD) characterized by frontotemporal lobar degeneration (FTLD) with TAR DNA-binding protein 43 (TDP-43) inclusions." (PMID 41373403, 2025). "TAR DNA-binding protein-43 (TDP-43) is a protein involved in RNA processing, implicated in the pathology of many neurodegenerative diseases, such as frontotemporal dementia (FTD)." (PMID 38137157, 2023). "The TARDBP gene mutations are found in approximately 5% of fALS cases, 1% of sALS cases, and 1% of frontotemporal dementia (FTD) cases." (PMID 35409306, 2022). "Pathologically, patients with pathogenic C9orf72 repeat expansions have cytoplasmic accumulation of TAR DNA-binding protein 43 (TDP-43), representing frontotemporal lobar degeneration (FTLD-TDP pathology)." (PMID 40138021, 2025). "To date, among a cohort of 97 unrelated patients with frontotemporal lobar degeneration characterized by TAR DNA-binding protein 43-kDa-positive inclusions (FTLD-TDP), fifty distinct GRN mutations have been identified." (PMID 41373403, 2025). "Intracellular deposition of TAR DNA binding protein (TDP-43) aggregates in the frontal and temporal lobes of the brain, resulting in frontotemporal lobar degeneration, microvacuole formation, and astrocytosis." (PMID 41516057, 2025). "In a mouse model of ALS and frontotemporal dementia, loss of the TAR DNA-binding protein 43 (TDP-43) in endothelial cells resulted in BBB dysfunction, including increased barrier permeability." (PMID 40463840, 2025). "Two patients were classified as TAR DNA-binding protein 43 (TDP-43)-positive frontotemporal lobar degeneration FTLD-TDP: one FTLD/MND-TDP; one FTLD-TDP related to a TANK-binding kinase 1 (TBK1) mutation." (PMID 40100387, 2025). "Mutations in the TARDBP gene which encodes the TAR-DNA-binding protein 43 (TDP-43) are implicated in the pathogenesis of ALS and Frontotemporal Lobar Degeneration (FTLD)." (PMID 39403566, 2024). "In particular, the authors found that patients with AD or frontotemporal dementia have aberrant accumulation of TAR-DNA binding protein-43 (TDP-43) in hippocampal astrocytes." (PMID 38515789, 2024). "Various family studies have shown a significant pathophysiological and clinical overlap between ALS and frontotemporal dementia (FTD), especially in cases related to variants in the C9ORF72, TARDBP, FUS, and VCP genes." (PMID 39596609, 2024). "Mutations of TMEM106B have been identified as genetic risk factors for neurodegenerative diseases including Frontotemporal lobar degeneration (FTLD) and limbic-predominant age-related TAR DNA binding protein 43 (TDP-43) encephalopathy." (PMID 37563705, 2023). "TDP-25 is a pathogenic aggregate-prone 25-kDa C-terminal protein of TARDBP/TDP-43 that has been identified in protein inclusions in several neurodegenerative diseases, including frontotemporal dementia and ALS." (PMID 36250672, 2023).